SIDT2 (SID1 transmembrane family member 2)
Description:
Mediates the translocation of RNA and DNA across the lysosomal membrane during RNA and DNA autophagy (RDA), a process in which RNA or DNA is directly imported into lysosomes in an ATP-dependent manner, and degraded. Involved in the uptake of single-stranded oligonucleotides by living cells, a process called gymnosis. In vitro, mediates the uptake of linear DNA more efficiently than that of circular DNA, but exhibits similar uptake efficacy toward RNA and DNA. Binds long double-stranded RNA (dsRNA) (500 - 700 base pairs), but not dsRNA shorter than 100 bp (By similarity).
Synonyms: CGI-40
Tractability: Antibody: UniProt places it where antibodies can reach, with high confidence; its Gene Ontology location is reachable by antibodies, with high confidence; UniProt predicts a signal peptide or a membrane-spanning region. PROTAC: ubiquitination databases record sites on it; its protein half-life has been measured.
Gene: Protein-coding gene on chromosome 11 (117,178,736 to 117,197,445, forward strand). Ensembl gene ENSG00000149577.
Subcellular location: Lysosome membrane; Cell membrane
Gene Ontology:
Molecular function: AP-1 adaptor complex binding; AP-2 adaptor complex binding; double-stranded RNA binding; nucleic acid transmembrane transporter activity; RNA transmembrane transporter activity
Biological process: RNA transport; RNA catabolic process
Cellular component: lysosomal membrane; lysosome; plasma membrane; membrane
Genetic constraint (gnomAD): Loss-of-function variants: 64 observed, 110.92 expected, observed/expected ratio (o/e) 0.58, 90% interval 0.47 to 0.71. The upper end of that interval is the gene's LOEUF score, 0.71, which puts it in group 2 of 6, group 1 being the genes least tolerant of losing a copy. Missense variants: 896 observed, 1,106.1 expected, observed/expected ratio (o/e) 0.81, 90% interval 0.77 to 0.86. Synonymous variants: 454 observed, 439.73 expected, observed/expected ratio (o/e) 1.03, 90% interval 0.95 to 1.12.
Homologues: Orthologues: macaque SIDT2 (99% identical), chimpanzee SIDT2 (98% identical), pig SIDT2 (97% identical), dog SIDT2 (96% identical), rabbit SIDT2 (96% identical), guinea pig SIDT2 (96% identical), rat Sidt2 (96% identical), mouse Sidt2 (95% identical), tropical clawed frog sidt2 (74% identical), zebrafish sidt2 (74% identical), Caenorhabditis elegans chup-1 (32% identical). Paralogues in human: SIDT1 (57% identical).
Diseases named in the same sentence as SIDT2 in open-access papers:
SIDT2 is named in the same sentence as 32 diseases in open-access papers, as found by Europe PMC text mining. Sharing a sentence is not in itself a finding about the gene and the disease. The quoted sentences say what the papers report.
metabolic syndrome (4 papers, 2018 to 2024). A cluster of metabolic risk factors for CARDIOVASCULAR DISEASES and TYPE 2 DIABETES MELLITUS. "Utilizing multi-SNP–multi-trait analysis, we found an association between the SIDT2 gene and metabolic syndrome or metabolic syndrome-component traits based on an association between metabolic syndrome and rs7107152 and rs1242229." (PMID 30382898, 2018). "We found an association between metabolic syndrome and an intronic SNP pair, rs7107152 and rs1242229, in SIDT2 gene at 11q23.3." (PMID 30382898, 2018). "The SNP set rs7107152 and rs1242229 on SIDT2 was also significant, supporting the association of SIDT2 with metabolic syndrome." (PMID 30382898, 2018). "For its effect on MetS risk, a multiple-phenotype GWAS has identified rs7107152 and rs1242229 SNPs of SIDT2 to be associated with metabolic syndrome risk in the Korean population, increasing HDL and triglyceride levels among metabolic syndrome-component traits." (PMID 35571045, 2022). "Across different demographic populations, SIDT2 has been shown to play a role in the development of metabolic syndrome and the eventual progression of coronary artery disease." (PMID 38275610, 2024). "All but four of the mapped genes (SIK3, SIDT2, UBASH3B, and CUX2) had been previously reported to be associated with metabolic syndrome, as indicated by a keyword search of “metabolic syndrome” in the GWAS catalog." (PMID 30382898, 2018). "The relation of the individual SNPs, including those on SIK3, SIDT2, UBASH3B, and CUX2, to metabolic syndrome was further examined by single-SNP–multi-trait analysis, adjusted for age and sex." (PMID 30382898, 2018).
coronary artery disease (2 papers, 2023 to 2024). "In a recent genome-wide association study, we identified a SIDT2 functional variant present in the Mexican population associated with high HDL-C levels and reduced premature coronary artery disease (CAD)." (PMID 37830567, 2023). "In a recent genome-wide association study, we identified a SIDT2 functional variant present in the Mexican population which was associated with HDL-C levels and premature coronary artery disease (CAD)." (PMID 37830567, 2023).
diabetes (2 papers, 2013 to 2025). "To explore the relationship between Sidt2 and diabetes, we first examined Sidt2 expression in the islet cells of diabetic db/db mice and found a significant reduction compared to that in wild-type (WT) mice." (PMID 40749831, 2025). "Collectively, Sidt2 expression was low in diabetes and closely related to glucose metabolism." (PMID 40749831, 2025). "Sidt2 may be another novel cellular protein responsible for impaired glucose tolerance seen in human diabetes." (PMID 23776622, 2013).
fatty liver disease (2 papers, 2022 to 2024). A reversible condition wherein large vacuoles of triglyceride fat accumulate in liver cells via the process of steatosis. "SID1 transmembrane family member 2 (SIDT2) deficiency induces ER stress and results in hepatic steatosis by upregulating SREBP1, sterol regulatory element binding transcription factor 1 (SREBF1) and fatty acid biosynthesis." (PMID 38310315, 2024). "In liver, for genes such as Sidt2 and Adk, they display cis- regulatory variation that is unique to the stressed liver and have been associated with human fatty liver disease." (PMID 35485945, 2022).
Glucose intolerance (2 papers, 2013 to 2020). Glucose intolerance (GI) can be defined as dysglycemia that comprises both prediabetes and diabetes. "Interestingly, the pathologic effects of in vivo Sidt2 deficiency are very similar to those of another lysosomal membrane protein, Synaptagmin-7, e.g. impaired insulin secretion, glucose intolerance, muscle fiber invasion by leukocytes and muscle weakness (our data unreported)." (PMID 23776622, 2013). "First insights into the roles of SIDT2 were derived from studies of Sidt2 knockout mice that showed elevated fasting glucose levels, glucose intolerance and decreased serum insulin levels." (PMID 33066450, 2020). "Intraperitoneal and oral glucose tolerance tests in Sidt2 knockout mice indicated glucose intolerance and decreased serum insulin level." (PMID 23776622, 2013).
hepatic disorders (2 papers, 2024 to 2025). "Furthermore, the SIDT2 gene product may contribute to SCD-related outcomes, as its dysregulation is linked to several metabolic traits associated with hepatic disorders, cardiovascular dysfunctions, and SCD-nephropathy." (PMID 41409427, 2025). "While some miRNAs have been identified as targeting SIDT2 in the context of liver diseases and cancer, no studies have yet reported on the miR-34a-5p-mediated regulation of SIDT2." (PMID 37902450, 2024).
Impaired glucose tolerance (2 papers, 2013 to 2020). An abnormal resistance to glucose, i.e., a reduction in the ability to maintain glucose levels in the blood stream within normal limits following oral or intravenous administration of glucose. "Sidt2 deficiency resulted in glucose metabolic dysfunction, which manifested as increased random blood glucose level and impaired glucose tolerance." (PMID 23776622, 2013).
Insulin resistance (2 papers, 2013 to 2020). Increased resistance towards insulin, that is, diminished effectiveness of insulin in reducing blood glucose levels. "However, there was no apparent insulin resistance in Sidt2 deficient mice." (PMID 23776622, 2013).
gastric cancer (1 paper, 2022). A primary or metastatic malignant neoplasm involving the stomach. "For RFS, high expression of OLFML2B, MT1M, and SIDT2 indicated a poor RFS of patients with GC, whereas gastric cancer patients with higher expression of CYP4X1 possessed better RFS from TCGA cohort." (PMID 36092901, 2022).
glomerulonephritis (1 paper, 2020). A renal disorder characterized by damage in the glomeruli. "Therefore, we used LPS to generate a glomerulonephritis cell model to study how LPS affects the expression of inflammatory factors and to determine the function of lysosomal membrane protein Sidt2 in inflammatory regulation." (PMID 32565723, 2020).
Lewy body dementia (1 paper, 2022). A progressive form of dementia characterized by the presence of protein deposits called Lewy bodies in the midbrain and cerebral cortex, and loss of cholinergic and dopaminergic neurons. "Added support for this relationship has recently come from a pathology study showing that the human SIDT2 protein was found co-localized with a-synuclein in Lewy Bodies of patients with PD and Lewy Body Dementia." (PMID 35984862, 2022).
Obesity (1 paper, 2018). Accumulation of substantial excess body fat. "SWIF(r) also identified SNPs within three other genes (PDGFRA, SIDT2, and PHACTR3) that have previously been associated with obesity and metabolism phenotypes." (PMID 29459739, 2018).
pancreatic cancer (1 paper, 2021). "Most downregulated RBPs include PAIP2B, SIDT2, PDCD4, AZGP1, and RNASE1, among which we report for the first-time involvement of PAIP2B, SIDT2, PDCD4, and RNASE1 in pancreatic cancer." (PMID 34912796, 2021).
vacuolar myopathy (1 paper, 2025). "SIDT2 knockout (KO) mice exhibit accumulation of ribosomal RNA (rRNA), messenger RNA (mRNA), and proteins in muscle tissue, leading to rimmed vacuolar myopathy, highlighting the critical role of SIDT2-dependent degradation in muscle homeostasis." (PMID 40842239, 2025).
kidney disease (3 papers, 2020 to 2025). "We expect that Sidt2 will provide a way to explore the pathogenesis and treatment of kidney diseases in the future." (PMID 34923568, 2021). "It is important to understand the function of lysosomal membrane protein Sidt2; however, the relationships between Sidt2 protein, tissue inflammation, and kidney disease remain to be further explored." (PMID 32565723, 2020).
tumor (3 papers, 2011 to 2024). "Loss of function studies has demonstrated an essential role for SIDT2 in the regulation of glucose metabolism, lipid metabolism, antiviral immunity, skeletal muscle homeostasis, and tumor development." (PMID 38237680, 2024). "But, the OS of MT1M was not statistically significant, while the OS of TNFAIP6 and SIDT2 were not in accordance with expression levels in tumor tissues." (PMID 36092901, 2022).
metabolic disorders (1 paper, 2024). "The implications of the genetic mutations of RAB6A and SIDT2 are unknown in our population of interest but have been associated with pulmonary, cardiac, and metabolic disorders." (PMID 38275610, 2024).
SIDT2 also shares sentences with these, for which no sentence is quoted: cancer (2 papers); Anxiety (1); breast adenocarcinoma (1); chronic kidney disease (1); chronic myeloid leukemia (1); Depression (1); diabetic nephropathy (1); endothelial dysfunction (1); Hepatic steatosis (1); hepatoma (1); Huntington disease (1); insulin secretion (1); kidney adenocarcinoma (1); leukemia (1); Nephropathy (1).